DNASE1L3 (deoxyribonuclease 1L3)
Description:
Has DNA hydrolytic activity. Is capable of both single- and double-stranded DNA cleavage, producing DNA fragments with 3'-OH ends (By similarity). Can cleave chromatin to nucleosomal units and cleaves nucleosomal and liposome-coated DNA. Acts in internucleosomal DNA fragmentation (INDF) during apoptosis and necrosis. The role in apoptosis includes myogenic and neuronal differentiation, and BCR-mediated clonal deletion of self-reactive B cells (By similarity). Is active on chromatin in apoptotic cell-derived membrane-coated microparticles and thus suppresses anti-DNA autoimmunity. Together with DNASE1, plays a key role in degrading neutrophil extracellular traps (NETs) (By similarity). NETs are mainly composed of DNA fibers and are released by neutrophils to bind pathogens during inflammation (By similarity). Degradation of intravascular NETs by DNASE1 and DNASE1L3 is required to prevent formation of clots that obstruct blood vessels and cause organ damage following inflammation (By similarity).
Synonyms: LSD; DHP2; DNAS1L3; D3; SLEB16
Tractability: Antibody: UniProt places it where antibodies can reach, with high confidence; UniProt predicts a signal peptide or a membrane-spanning region; its Gene Ontology location is reachable by antibodies, with medium confidence. PROTAC: a small molecule that binds it is known.
Target class: Enzyme; Hydrolase
Gene: Protein-coding gene on chromosome 3 (58,192,257 to 58,214,697, reverse strand). Ensembl gene ENSG00000163687.
Subcellular location: Nucleus; Endoplasmic reticulum; Secreted
Gene Ontology:
Molecular function: protein binding; calcium ion binding; deoxyribonuclease I activity; DNA binding; DNA nuclease activity; catalytic activity; DNA endonuclease activity; endonuclease activity
Biological process: apoptotic DNA fragmentation; DNA metabolic process; neutrophil activation involved in immune response; programmed cell death involved in cell development; regulation of acute inflammatory response; regulation of neutrophil mediated cytotoxicity; DNA catabolic process
Cellular component: endoplasmic reticulum; extracellular region; nucleus
Genetic constraint (gnomAD): Loss-of-function variants: 26 observed, 32.17 expected, observed/expected ratio (o/e) 0.81, 90% interval 0.59 to 1.12. The upper end of that interval is the gene's LOEUF score, 1.12, which puts it in group 4 of 6, group 1 being the genes least tolerant of losing a copy. Missense variants: 333 observed, 350.42 expected, observed/expected ratio (o/e) 0.95, 90% interval 0.87 to 1.04. Synonymous variants: 120 observed, 128.22 expected, observed/expected ratio (o/e) 0.94, 90% interval 0.81 to 1.09.
Gene-disease validity (ClinGen):
ClinGen rates the evidence that DNASE1L3 causes each of these diseases.
autosomal systemic lupus erythematosus type 16 (autosomal recessive): Definitive.
Homologues: Orthologues: chimpanzee DNASE1L3 (99% identical), macaque DNASE1L3 (96% identical), pig DNASE1L3 (87% identical), rat Dnase1l3 (84% identical), dog DNASE1L3 (83% identical), rabbit DNASE1L3 (83% identical), mouse Dnase1l3 (81% identical), guinea pig DNASE1L3 (81% identical), tropical clawed frog dnase1l3 (56% identical). Paralogues in human: DNASE1 (41% identical), DNASE1L2 (41% identical), DNASE1L1 (39% identical).
Diseases named in the same sentence as DNASE1L3 in open-access papers:
DNASE1L3 is named in the same sentence as 69 diseases in open-access papers, as found by Europe PMC text mining. Sharing a sentence is not in itself a finding about the gene and the disease. The quoted sentences say what the papers report.
lupus (28 papers, 2014 to 2025). "Three families containing seven lupus patients were identified with autosomal recessive lupus due to a homozygous frameshift variant in DNASE1L3, a lupus-associated variant known to have high prevalence in Oman." (PMID 40465409, 2025). "Familial forms of HUVS and HUVS associated with systemic lupus erythematosus (SLE) have been associated with mutations in DNASE1L3." (PMID 40026936, 2025). "In the same pathway, another gene, DNASE1L3, has been associated with a lupus phenotype, with about 50 patients reported in the literature." (PMID 39964335, 2025). "Mouse models suggest Dnase1l3 deficiency leads to the development of antibodies to double‐stranded DNA and chromatin, resulting in a lupus‐like phenotype." (PMID 39964335, 2025). "We also observe by spatial transcriptomics resolved to single cells that the most enriched transcript in FAE and SED encodes the lupus associated autoantigen DNASE1L3, which is expressed together with C1q." (PMID 38744839, 2024). "A disease associated with deficiencies of Dnase1 and Dnase1l3 in mouse is systemic lupus erythematosus (SLE)." (PMID 38255187, 2023). "A DNASE1L3 deficiency, for example, results in chronic inflammation with respect to anti-DNA responses and autoimmune diseases such as systemic lupus erythematosus." (PMID 37190296, 2023). "Supporting a role of DNases in autoimmunity, deficiency in DNase1 or DNase1L3 triggers lupus-like symptoms in ANA-positive glomerulonephritis and promotes kidney deposition of immune complexes and complement factor C3 in genetically modified mice." (PMID 37287977, 2023). "Deficiencies in two endonucleases that specifically target DNA, Dnase1 and Dnase1l3, are associated with systemic lupus erythematosus (SLE)." (PMID 38255187, 2023). "Mice deficient in either DNase1 or DNase1L3 expression develop features similar to other mouse models of lupus." (PMID 29922296, 2018). "DNASE1L3 deficiency has been shown to be clearly associated with a lupus phenotype." (PMID 40455313, 2025). "We identified a novel DNASE1L3 gene variant leading to monogenic lupus and." (PMID 37848930, 2023). "Interestingly, DNASE1L3 is genetically associated with multiple autoimmune phenotypes including systemic lupus erythematosus (SLE), systemic sclerosis, and scleroderma." (PMID 34200671, 2021). "DNase1l3-deficient mice develop autoantibodies and signs of a lupus-like autoimmune disease." (PMID 34497606, 2021). "A defining feature of systemic lupus erythematosus (SLE) is loss of tolerance to self-DNA, and deficiency of DNASE1L3, the main enzyme responsible for chromatin degradation in blood, is also associated with SLE." (PMID 38888971, 2024). "This system that is driven by microbial ligands could be impacted by DNASE1L3 deficiency in lupus." (PMID 38744839, 2024). "Rare and potentially pathogenic variants in the lupus associating genes C1s, C2, DNASE1 and DNASE1L3 as well as CFHR4 were discovered in Cases 4–6 diagnosed with early-onset SLE in the present series." (PMID 35964089, 2022). "These included patients with familial monogenic systemic lupus erythematosus (SLE) with DNASE1L3 mutations and many cancers with downregulated DNASE1L3 expression." (PMID 39697357, 2022). "Our findings of DNASE1L3’s effects on cell-free eccDNA characteristics in this study might provide yet another potential biomarker for early diagnosis or monitoring of diseases related to DNASE1L3 deficiency, such as systemic lupus erythematosus." (PMID 35451374, 2022). "Similarly, the loss of DNase1 or DNase1L3 in mice is associated with a lupus‐like pathology." (PMID 36098213, 2022). "One genetic cause of pediatric-onset SLE is Dnase1L3 (Dnase γ) deficiency, characterized by anti-dsDNA antibodies, low complement, antineutrophil cytoplasmic antibodies, no gender bias, and a strong incidence of lupus nephritis." (PMID 28533778, 2017).
lupus (continued). "Notably, both C1Q and DNASE1L3 can be the target of autoantibodies in patients with genetically complex “classic” SLE and are associated with a higher risk of lupus nephritis." (PMID 39964335, 2025). "We show that in this location double negative 2 B cells interact with dendritic cells co-expressing the lupus autoantigens DNASE1L3 and C1q and microbicides." (PMID 38744839, 2024). "The constellation of findings supports the notion that DNASE1 and DNASE1L3 activity is a protective mechanism for the development of autoimmunity in lupus." (PMID 38888971, 2024). "An enzyme biologic with dual-acting DNASE1/DNASE1L3 activity prevents autoimmunity and death in lupus models, with implications for other diseases characterized by aberrant DNA accumulation." (PMID 38888971, 2024). "Our final murine studies examined the relative contributions of DNASE1 and DNASE1L3 to mortality present in the pristane-induced lupus model, conclusively demonstrating that DNASE1L3 activity drives this phenotype." (PMID 38888971, 2024). "For instance, we know about the existence of cases of systemic lupus erythematosus caused by monogenic mutations in the C1qA, B, C, C1R, DNASE1, DNASE1L3, and ACP5 genes, among many other predisposing genetic variations." (PMID 36900420, 2023). "Recently, a significant number of genes have been implicated in monogenic lupus, such as several complement deficiencies, ACP5, DNASE1, DNASE1L3, PRKCD, RAG2 genes, etc.." (PMID 34796153, 2021). "Loss of function mutations in DNASE1L3 are responsible for a familial form of SLE which is characterized by the presence of anti-dsDNA antibodies and lupus nephritis, and mechanistic studies have directly implicated DNASE1L3 deficiency as a cause of anti-dsDNA antibody development." (PMID 34200671, 2021). "Notably, we found that the biologic prevented the development of lupus in Dnase1–/–Dnase1L3–/– double-knockout mice and rescued animals from death in pristane-induced lupus." (PMID 38888971, 2024). "Whilst there was strong colocalisation of DNASE1L3 and C1Q, and to some extent C3 and C1R, there was no colocalisation between DNASE1L3 and the other lupus related genes, including genes associated with apoptosis." (PMID 38744839, 2024). "In addition, lupus-prone MRL and NZB/W F1 mice are deficient in DNase1L3, and the sole deficiency of this enzyme leads to lupus-like disease in mice." (PMID 36941260, 2023). "Unexpectedly, during the clinical and molecular characterization of autoantibodies to the endonuclease DNase1L3 in patients with systemic lupus erythematosus (SLE), we identified a subset of neutralizing anti-DNase1L3 antibodies previously catalogued as anti-dsDNA." (PMID 36941260, 2023). "We crossed Dnase1L3–/– mice with Dnase1–/– mice to generate Dnase1–/–Dnase1L3–/– double-knockout (DKO) mice on a C57BL/6 background to develop a genetic lupus murine model lacking both DNASE1 and DNASE1L3." (PMID 38888971, 2024). "Pediatric-onset systemic lupus erythematosus arises in humans and mice lacking the endonuclease Dnase1L3." (PMID 28533778, 2017).
Autoimmunity (12 papers, 2017 to 2025). The occurrence of an immune reaction against the organism's own cells or tissues. "Our combined studies validate 1833 as an enzyme therapeutic for patients with autoimmune disorders associated with DNASE1L3 deficiency." (PMID 38888971, 2024). "In order to study the epistatic effects of genes involved in inhibitory signaling and immune complex clearance on autoimmunity, Siglecg deficient mice were crossed either with Dnase1l3 deficient mice or with a newly generated Dnase1 deficient mouse line." (PMID 36969253, 2023). "Further differentially expressed genes of interest are Klk1 and DNase1l3, that are both associated with autoimmunity." (PMID 34497606, 2021). "Although somatic hypermutation can contribute to both gain and loss of self-reactivity and autoimmunity may be caused by both follicular and extrafollicular pathways, molecular defects (i.e., DNASE1L3 and IKZF1 deficiency) have been shown to drive extrafollicular SLE." (PMID 34889940, 2022). "Partial loss of Dnase1L3 activity in humans can lead to the related autoimmune condition called hypocomplementemic urticarial vasculitis, indicating that Dnase1L3 protects humans from autoimmunity." (PMID 28533778, 2017). "DNase1l3 is secreted by innate immune cells and may play a critical role in maintaining tissue homeostasis and preventing the development of autoimmunity." (PMID 37251563, 2023). "Deoxyribonuclease 1 like 3 (DNASE1L3) is a secreted DNASE1-like nuclease that can digest DNA in chromatin, and its deficiency may lead to anti-DNA responses and autoimmunity in both humans and mice." (PMID 31977318, 2020). "Hence, this also suggests that DNASE1L3 might have a protective role from autoimmunity." (PMID 37813633, 2023). "However, as autoimmunity in DNase1L3KO mice is independent of the cytosolic DNA sensor STING, it indicates that the anti-DNA responses are specifically due to the extracellular DNase function of DNase1L3." (PMID 31354738, 2019).
autoimmune disease (11 papers, 2019 to 2025). A disorder resulting from loss of function or tissue destruction of an organ or multiple organs, arising from humoral or cellular immune responses of the individual to their own tissue constituents. "Our findings have important implications for the treatment of patients with autoimmune diseases associated with genetic and acquired DNASE1L3 deficiency." (PMID 38888971, 2024). "Deficiency in DNASE1L3 has been associated with development of autoimmune diseases in both humans and mice." (PMID 37581941, 2023). "Despite a well-established causal relationship between Dnase1l3 deficiency and autoimmune diseases, little is known about the link between Dnase1l3 deficiency, antitumor immunity, and tumorigenesis/tumor progression." (PMID 37581941, 2023). "The identification of genetic mutations in DNASE1L3 provides valuable insights into the pathogenesis of SLE, as DNASE1L3 is involved in the regulation of DNA breakdown, and mutations in this gene are associated with increased susceptibility to autoimmune diseases like SLE." (PMID 40182376, 2025). "In conclusion, our studies suggest that enhancing the plasma activity of DNASE1 and DNASE1L3 with our bioavailable enzyme biologic is likely to carry significant therapeutic benefit in patients with autoimmune disease associated with impaired DNASE1L3 activity." (PMID 38888971, 2024). "Deficiency of DNASE1L3 leads to development of autoimmune diseases in both humans and mice." (PMID 37581941, 2023). "Interestingly, despite their differing typical localizations—DNASE1L3 being extracellular and PLD4 intracellular—both DNASE1L3 and PLD4 are associated with human autoimmune diseases and display similar phenotypes in genetically modified mice." (PMID 40811510, 2025). "Our findings suggest that autoimmune diseases characterized by aberrant DNA accumulation, such as SLE, can be effectively treated with a replacement DNASE tailored to bypass pathogenic mechanisms, both genetic and acquired, that restrict DNASE1L3 activity." (PMID 38888971, 2024). "Specifically, cluster 3 cDC2 isolated from MC38 tumors in Dnase1l3-KO mice had decreased GSVA scores in gene sets associated with proteasome, graft-host interaction, autoimmune diseases, and antigen processing and presentation, compared with those from WT mice (cDC2, cDC3)." (PMID 37581941, 2023). "Previous studies have reported that the serum concentration of DNASE1L3 protein is decreased in dermatomyositis, SLE, and rheumatoid arthritis, suggesting that DNASE1L3 may be involved in the development of autoimmune diseases." (PMID 31977318, 2020). "The discovery of anti-DNase1L3/dsDNA antibodies renews interest in better understanding the significance of cross-reactivity among autoantibodies in SLE, which may shed light on the origin and heterogeneity among the wide range of autoantibodies found in this autoimmune disease." (PMID 36941260, 2023).
hepatocellular carcinoma (10 papers, 2020 to 2025). A malignant tumor that arises from hepatocytes. "Higher expressions of DNASE1L3 were recently correlated to longer overall survival after radical resection of hepatocellular carcinoma." (PMID 37190296, 2023). "Hepatoma cells lines were found to possess depressed DNASE1L3 expression compared with immortalized liver cell line L02." (PMID 34975319, 2022). "The authors found a downregulation of DNASE1L3 in hepatocellular carcinoma cells and hypothesized that decreased DNASE1L3 activity was responsible for decrease of “CCCA”-bearing cfDNA fragments in plasma of patients with hepatocellular carcinoma." (PMID 36010184, 2022). "However, the role of DNASE1L3 in hepatocellular carcinoma (HCC) and its molecular basis remains to be further investigated." (PMID 35748106, 2022). "Deoxyribonuclease 1 like 3 (DNASE1L3) facilitates double-strand deoxyribonucleic acid (dsDNA) breaks generation and activates AIM2 pathway during sorafenib treatment to trigger PANoptosis and decrease the hepatocellular carcinoma cell survival." (PMID 40721869, 2025). "To elucidate the role of DNASE1L3 in HCC, we categorized RNA-seq raw data from 424 liver hepatocellular carcinoma (LIHC) samples obtained from the TCGA database into two groups: the top 100 samples with high DNASE1L3 expression and the top 100 samples with low DNASE1L3 expression." (PMID 39479454, 2024).
liver cancer (8 papers, 2020 to 2024). An epithelial or non-epithelial malignant neoplasm that arises from the liver. "DNAJC13 promoted breast cancer progression, and the overexpression of DNASE1L3 was a good prognostic index for liver cancer and renal cancer." (PMID 33592580, 2021). "As shown, the expression of DNASE1L3 in liver cancer tissues was significantly lower than that of adjacent normal tissues (p < 0.001)." (PMID 31977318, 2020). "Furthermore, our analysis of the liver cancer database suggests that higher expression of DNASE1L3 is positively correlated with better prognosis following both sorafenib therapy and immunotherapy." (PMID 39479454, 2024). "Deoxyribonuclease 1-like 3 (DNASE1L3) is secreted by macrophages and could be an independent prognostic marker to predict survival outcomes in patients following radical liver cancer resection." (PMID 37950156, 2023). "The expression differences of the six Hub genes C3, CTNNB1, CYBC1, DNASE1L3, IRAK1, and SERPINE1 between human liver cancer cell lines and normal liver cell lines are statistically significant." (PMID 39055701, 2024). "Among the six hub genes, C3 and DNASE1L3 are relatively low expressed in HCCLM3 and 97H liver cancer cell lines, while CTNNB1, CYBC1, IRAK1, and SERPINE1 are relatively overexpressed in liver cancer cell lines." (PMID 39055701, 2024). "In cancer samples such as colorectal cancer, gastric cancer, head and neck cancer, and liver cancer, DNASE1L3 was significantly downregulated compared with normal tissues." (PMID 34157681, 2021).
lupus nephritis (6 papers, 2021 to 2025). Glomerulonephritis in the context of systemic lupus erythematosus. "Instead, kidney LECs express a repertoire of other molecules, including DNASE1L3, a molecule involved in extracellular DNA clearance and deficiency of which is implicated in lupus nephritis." (PMID 40663403, 2025). "Mechanistically, DNase 1 deficiency, neutralizing anti-DNase1L3 antibodies, and DNASE1L3 mutations converge to impair extracellular chromatin degradation, facilitating NETs accumulation, immune complex formation, and lupus nephritis." (PMID 41335221, 2025). "DNASE1L3 was significantly upregulated in the tubulointerstitium of patients with lupus nephritis (n = 31) compared with controls (n = 8, mean difference in log2 expression = 1.1 ± 0.34–1.9, P = 0.0013)." (PMID 40663403, 2025). "The accumulation of microparticles containing extracellular DNA can induce B cells to produce autoantibodies against C1q or DNASE1L3, which also contribute to the development of SLE nephritis." (PMID 40455313, 2025). "Consistently, loss-of-function variations in DNASE1 or DNASE1L3 predispose to SLE, suggesting that undigested DNAs activate B cells, macrophages and DCs in Dnase1l3−/− mice, leading to lupus nephritis." (PMID 40037613, 2025).